ETS1 (ETS proto-oncogene 1, transcription factor)
Diseases named in the same sentence as ETS1 in open-access papers (continued):
Sharing a sentence is not in itself a finding about the gene and the disease.
cancer (continued). "We performed ETS-1 inhibition in the Panc-1 cancer cell line, which exhibited relatively high expression of ETS-1." (PMID 25421630, 2015). "ETS1 has been described in literature to be involved in regulation of and by miRNAs which are involved in cancer." (PMID 26627005, 2015). "The effect of transcriptional silencing of ETS-1 on the motility of Panc-1 cancer cells was measured in scratch and adhesion assays." (PMID 25421630, 2015). "Perhaps, we proposed that integrin αvβ6 regulated the cancer cell malignant biological behavior through αvβ6—ERK—Ets-1 signal pathway." (PMID 25264483, 2014). "Ets1 has been shown to stimulate cancer cell proliferation and inhibit endothelial cell proliferation through regulation of p21." (PMID 24897113, 2014). "Ets1 has been well studied in the regulation of different aspects of cancer cell behavior, including extracellular matrix remodeling, invasion and angiogenesis." (PMID 24897113, 2014). "Granted that ETS-1 plays an important role in multiple cancers,it is valuable to identify more regulators of ETS-1." (PMID 24857950, 2014). "Both transcriptional factor Ets-1 and integrin αvβ6 play an important role in the development and progression of cancer." (PMID 25264483, 2014). "Ets1 is an essential transcription factor for a variety of physiological processes, such as immunity and cancer development." (PMID 25380315, 2014). "Several reports also demonstrated that the u-PA and MMPs which were downstream genes of ETS-1 are involved in chemo-resistant, aggressiveness, progression and prognosis in cancer cells." (PMID 24857950, 2014). "As an interesting example, the v-ets erythroblastosis virus E26 oncogene homolog 1 product (Ets1), which plays essential roles in a wide range of important biological processes, such as cancer and immunity, has been extensively studied." (PMID 25380315, 2014). "Our laboratory recently identified Ets-1 as a key regulator of cancer metabolism that encourages glycolytic dependence and decreases oxidative phosphorylation." (PMID 24238102, 2013). "These pathways are all important in regulating oxidative stress and cellular redox state, thus it is not surprising that we also observed decreased ROS levels and increased GPX activity in Ets-1 overexpressing cancer cells." (PMID 24280356, 2013). "Immunohistochemical staining was performed to observe the expression of cyclin D1 and Ets1 in these cancer specimens." (PMID 23383271, 2013). "To demonstrate PARylation in human cancer cells, we generated a HeLa cell line, obtained by retroviral infection, that stably expresses Ets-1 tagged with a streptavidin-binding peptide (SBP)." (PMID 23405229, 2013). "Our analysis shows that the expression of Ets-1 in cancer cells results in a transcriptional program that confers enhanced cancer progression and development through the alteration of metabolism and redox status." (PMID 24280356, 2013). "Though we have not validated this association functionally, the upregulation of fatty acid desaturation by Ets-1 represents another potential mechanism by which this transcription factor enhances cancer progression, and warrants further investigation." (PMID 24280356, 2013). "In this study, we demonstrate that PARP-1 negatively controls the level of Ets-1 proteins in cancer cells via PARylation." (PMID 23405229, 2013). "Consistent with a role for miR-1 in dysregulation of Ets1 in cancer, a study published after we chose Ets1 as a candidate showed that Ets1 is targeted by miR-1 in HepG2 cells." (PMID 23646287, 2013). "The diverse functional roles of Ets-1 in a variety of cancer types truly illustrate the potential use of Ets-1 inhibition as an effective therapeutic target, although the limitations to such an approach are significant." (PMID 24238102, 2013). "To do so, we used the promoter of the matrix metalloprotease stromelysin-1, which is a well-studied Ets-1 target gene involved in cancer cell migration and invasion." (PMID 23405229, 2013).
cancer (continued). "In accordance with these results, cellular oxygen consumption was significantly decreased in cancer cells expressing Ets-1, suggesting that electrons are passing through the electron transport chain and generating ROS at a decreased rate." (PMID 24280356, 2013). "The importance of Ets-1 in cancer has been investigated extensively with regards extracellular matrix remodeling and angiogenesis." (PMID 24238102, 2013). "Under PARylation inhibition, Ets-1 transcriptional activity is enhanced which correlates with Ets-1 proteins accumulation in cell nuclei and an increase in DNA damage that leads to cancer cell death." (PMID 23405229, 2013). "Thus, Ets-1-mediated alterations in glutathione antioxidant activity likely account, at least in part, for the associations observed with overexpression of this factor and poor prognosis, advanced malignancy, and enhanced metastatic potential in several types of cancer." (PMID 24238102, 2013). "Restoration of miR-9-mediated down-regulation of cyclin D1 and Ets1 by transient transfection, rescued the cancer cells from decrease in proliferation, migration and invasion." (PMID 23383271, 2013). "Ets-1 regulates the expression of various proteases that are critical to matrix reorganization and cancer cell invasion." (PMID 22971289, 2012). "Chromatin immunoprecipitation, promoter mutagenesis and target specific siRNAs were then utilized to identify ETS1 as the transcription factor regulating EGFR-MEK1/2-dependent CIP2A expression in human cancers." (PMID 21445343, 2011). "Together, these results provide concrete experimental evidence of ETS1 being the transcription factor mediating EGFR-MEK1/2 dependent regulation of CIP2A in cancer cells." (PMID 21445343, 2011). "Immunohistochemistry staining showed that Ets-1 was strongly expressed in cancer cells and stroma but weakly expressed in benign tumors." (PMID 21439064, 2011). "Functional assays confirmed that Ets-1 over-expressing cancer cells displayed reduced oxidative phosphorylation capabilities, as well as enhanced reliance on glycolysis for cellular energy." (PMID 21042593, 2010). "The prognosis is also significantly worse in those patients with high levels of Ets-1 expression in the tissues derived from the primary cancer." (PMID 20454645, 2010). "Taken together, our findings indicate that Ets-1 is a key transcription factor involved in regulating metabolic and oxidative stress in cancer cells." (PMID 21042593, 2010). "The link between Ets-1 and cancer invasiveness can potentially be explained by the list of known target genes regulated by this transcription factor." (PMID 21042593, 2010). "Taken together, these trends suggest that Ets-1 is an important transcriptional regulator not only in the catabolic, but also anabolic metabolic transitions of cancer cells that ultimately promote tumourigenesis." (PMID 21042593, 2010). "Our laboratory and that of others have highlighted the importance of Ets-1 in the regulation of different aspects of cancer cell behaviour, including extracellular matrix remodeling, invasion, angiogenesis, and drug resistance." (PMID 21042593, 2010). "Because of its roles in the transcriptional regulation of MMPs, Ets-1 is a candidate mediator of cancer invasion and metastasis." (PMID 17980029, 2007). "All these findings, taken together, suggest that Ets-1 is likely to play a key role in cancer progression, especially angiogenesis and invasion." (PMID 15365563, 2004). "Likewise, our previous studies have demonstrated that PARP‐1 interacts physically with Ets‐1 and negatively regulates its level in cancer cells via PARylation." (PMID 39778077, 2025). "Among the various molecular players involved in the pathogenesis of PTC, the transcription factor ETS1 has garnered attention because of its roles in proliferation, differentiation, and apoptosis, the cell processes critical to cancer development, progression, and metastasis." (PMID 39941022, 2025).
cancer (continued). "This preliminary study demonstrates that PARPi‐induced oxidative stress correlates with Ets‐1 expression, which might represent a biomarker potentially able to identify the most sensitive cancer cells for treatment with PARPi." (PMID 39778077, 2025). "Therefore, ETS-1 is considered a promising therapeutic target in cancer treatment, and its comprehensive study holds significant scientific and clinical importance." (PMID 40181983, 2025). "As research into the functional mechanisms of ETS-1 progresses and therapeutic technologies advance, ETS-1 could emerge as a key target for cancer immunotherapy." (PMID 40181983, 2025). "We next investigated the role of ETS1 in promoting cancer metastasis in vivo." (PMID 40777467, 2025). "ETS1 promotes the growth and metastasis of different cancer cell lines." (PMID 40948762, 2025). "Indeed, PARP‐1 regulates the transcriptional activity of many factors involved in cancer (e.g., Ets‐1)." (PMID 39778077, 2025). "ETS1 and MMP9 can regulate EMT and have both been frequently associated with cancer metastasis." (PMID 38732189, 2024). "However, LINC00922 overexpression blocked SIRT3 recruitment to the ETS1 promoter and then increased ETS1 transcription by increasing H3K27cr level in this region, ultimately promoting cancer metastasis." (PMID 37789393, 2023). "Additionally, 17β-estradiol (E2) activates EGFR, thus stimulating the MEK1/2 and PI3K pathways and further increasing the expression of CIP2A/p90 through the MEK1/2-induced transcription factor Ets1 to enhance the proliferation of cancer cells." (PMID 36911405, 2023). "The cBioPortal was applied to explore the mutation landscape of ETS1 and ETS2 across cancers." (PMID 36760475, 2023). "Moreover, we detected miR-222-3p and ETS1 mRNA levels in 20 pairs of HBV-HCC cancer and paracancerous tissues to find ETS1 mRNA levels were negatively correlated with the miR-222-3p levels in both HBV-positive HCC tissues by cox regression." (PMID 36690646, 2023). "ETS1 harbored a higher ratio of deep deletion than ETS2 in several cancers." (PMID 36760475, 2023). "A pan-cancer prognostic analysis of ETS1 and ETS2 was assessed using the KM plotter." (PMID 36760475, 2023). "Research evidence suggests that ETS1 may accelerate the development of cancer by influencing the function of the PI3K/AKT/mTOR signaling pathway." (PMID 37046729, 2023). "ETS1 was increased in several cancers, while ETS2 was decreased in several cancers." (PMID 36760475, 2023). "ETS1 was positively correlated with several infiltrating immune cells across cancers." (PMID 36760475, 2023). "In addition, VEGFA and B, their receptors KDR and FLT1, and downstream TFs, including KLF4 and ETS1, were found in this analysis as targets of cooperative ENHs, in line with the pivotal role of angiogenesis in promoting cancer metastatic spreading." (PMID 37408506, 2023). "Furthermore, in this study, TMB and MSI were found to have a significant connection with ETS1 in various cancers." (PMID 35463077, 2022). "However, as a transcription factor, Ets1 interacts with other regulatory factors and plays an important role by altering gene transcription in the control of cancer-relevant processes." (PMID 36305724, 2022). "Moreover, H2O2 treatment increases Ets-1 expression by NRF2 binding to ARE in the Ets-1 promoter, suggesting that Ets-1 is clearly modulated by ROS in cancer cells via NRF2 signalling." (PMID 35453348, 2022). "ETS-1 is generally highly expressed in many malignant tumors." (PMID 36211008, 2022). "This study provided more information about the role of ETS1 in cancer immunotherapy." (PMID 35463077, 2022). "Furthermore, the bioinformatics research revealed some interesting details concerning ETS1's function in cancer." (PMID 35463077, 2022). "Furthermore, Immunohistochemistry (IHC) staining of HCC tissue microarrays showed an increase in Ets-1 expression in advanced stages of cancer." (PMID 35789155, 2022).
cancer (continued). "We also investigated whether ETS1 was related to the level of immune infiltration in diverse cancers." (PMID 35463077, 2022). "ETS1 may be an essential new target or biomarker for cancer diagnosis since it can be a sensitive indicator." (PMID 35463077, 2022). "The linkages between ETS1 and TME, as well as its association with immunological processes/elements and the major histocompatibility complex, were explored to effectively understand the role of ETS1 in cancer immunotherapy." (PMID 35463077, 2022). "This suggested that ETS1 might have an indirect influence on the immunotherapeutic response to past cancers." (PMID 35463077, 2022). "Moreover, higher expression of Ets-1 favors cancer cell growth and proliferation by regulating metabolism and oxidative stress." (PMID 35789155, 2022). "An interesting question is whether the CRISPReader system can exert its anti-cancer ability against a variety of tumors by sensing the broad-spectrum transcription factor Ets-1." (PMID 34124154, 2021). "Because ETS-1 is a transcription factor that functions as a primary regulator in the metastasis process by mediating the expression of MMP to degrade the ECM of cancer cells and promote the invasion or migration of cancer cells, the effect of TPX2 on the invasion of PC-3 cells was examined." (PMID 34123781, 2021). "Previously, it had been exhibited that RARα could bind to E26 transformation-specific-1 (Ets1) promoter and induced the expression of Ets-1 mRNA and protein levels in cancer cells." (PMID 32984354, 2020). "The KDM3A and Ets1 upregulated transcriptomes, alone and together, also contain numerous additional genes implicated in cancer promotion, which are not dependent on PAX3/FOXO1 for expression." (PMID 32697014, 2020). "Ets1 is a known promoter of invasive and metastatic phenotypes in other cancers." (PMID 32697014, 2020). "Moreover, KDM3A and Ets1 also positively control a group of genes commonly overexpressed in pediatric cancers relative to normal tissues (‘Whiteford Pediatric Cancer Markers’)." (PMID 32697014, 2020). "It should be noted that if ETS-1 can confer cisplatin resistance, it may be cancer- or cell-type specific." (PMID 31118072, 2019). "Of note, it was reported that miR-126 could activate the MAPK/ERK pathway and MAPK/ERK signaling contributes to the upregulation of downstream transcription factor Ets-1 in cancer cells." (PMID 31281371, 2019). "Taken together, PKM2 facilitates cancer invasion via ETS-1 pathway in OSCC." (PMID 31071178, 2019). "ETS1 has versatile roles during the cellular processes of various types of cancers." (PMID 31860871, 2019). "Furthermore, ETS-1 induces cancer cell invasion and regulates epithelial-to-mesenchymal transition (EMT), thereby leading to drug resistance and neovascularization." (PMID 30970566, 2019). "Next, we demonstrated that the decrease in Daxx levels following HSP27 downregulation in human cancer cells resulted from decreased binding of ETS1 and SP1 to the Daxx promoter (left, middle), whereas HSP25 downregulation in murine cells increased ETS1 binding to the Daxx promoter (right)." (PMID 31615977, 2019). "Several studies have revealed that ETS1 is over-expression in drug resistant cancer cells." (PMID 29950928, 2018). "We observed that the promoter sequences of these translation elongation factor genes harbour binding sites for transcription factors which are commonly deregulated in the pathogenesis of human cancers, such as cFos, cJun, c-Ets1, Sp1, Sp3, Pax2 and, Pax6 among others." (PMID 29342219, 2018). "In addition, positive expression correlation of Ets-1 with pancEts-1 or ERG was observed in many types of cancers in public datasets derived from GEO." (PMID 29773901, 2018). "Another report showed that CXCR1 could up-regulate matrix metalloproteinase-9 (MMP-9) expression by activating JNK/c-Jun and ERK/Ets-1 pathways, thus resulting in more aggressive biological characteristics of cancer cells." (PMID 27780937, 2017).
cancer (continued). "Several reports have indicated the coexpression of HIF‐1α and ETS‐1 in cancer." (PMID 28236660, 2017). "Furthermore, ETS-1 is expressed in many tumors and activates many cancer related genes that promote the malignant transformation and progression of tumors, including invasion, metastasis and neoangiogenesis." (PMID 27036016, 2016). "ETS-1 is a signal-dependent transcription factor that is overexpressed in some cancers." (PMID 26826553, 2016). "The oncogenic signal ETS-1 actuates this artificial cancer-specific promoter." (PMID 26743236, 2016). "α3β1 has been implicated as a potential marker protein for cells undergoing enhanced EMT or for cancer cells with aggressive phenotypes, and the transcription factor Ets-1 may play role in transcriptional activation of the α3 subunit gene." (PMID 24950714, 2014). "High ETS1 levels correlate with poor prognosis in cancer of the breast, ovary and cervix." (PMID 24602286, 2014). "Nevertheless, Ets-1 expression sensitised cancer cells to PJ-34 toxicity to a great degree." (PMID 23405229, 2013). "Some of the upregulated genes are related to CSC/’cancer stemness’ such as CXCR4, CD133, EPCAM and SOX9, while others are associated with apoptosis (FASLG, TJP2, DUSP4), the MAPK pathway (MAP2K4, DUSP4), and chemoresistance (MMP1, an ETS1 target gene)." (PMID 24069258, 2013). "Furthermore, our results give new insight into Ets-1 regulation in cancer cells and its link to DNA-repair proteins." (PMID 23405229, 2013). "In addition, the levels of phosphorylated retinoblastoma (pRB, a downstream effector of cyclin D1) and matrix metalloproteinase 9 (MMP-9, a downstream gene of Ets1) were decreased in miR-9 over-expressing cancer cells." (PMID 23383271, 2013). "In addition, an inverse correlation between miR-9 expression and Ets1 transcript levels was also noted in these cancer tissues (P<0.001)." (PMID 23383271, 2013). "In conclusion, we provide evidence that Ets-1 may be a potential new candidate as a biomarker of cancer cell sensitivity to PARP-1 inhibition." (PMID 23405229, 2013). "Finally, we demonstrated that Ets-1 accumulation subsequent to PARylation inhibition sensitises cancer cells and leads to their death." (PMID 23405229, 2013). "As well as TRA2B gene amplification, the expression levels of the ETS-1 transcription factor provide a possible mechanism through which Tra2β might be upregulated in cancer cells." (PMID 23935626, 2013). "Interestingly, we have shown that GSH depletion following SAS treatment correlates with Ets-1 overexpression levels, where cancer cells that express high levels of Ets-1 display greatly decreased GSH levels following Sxc- blockade." (PMID 24238102, 2013). "Aggressive cancer cells are often chronically exposed to high levels of oxidative stress, which could explain why Ets-1 is commonly upregulated in these cancers." (PMID 24280356, 2013). "To determine the consequences of Ets-1 accumulation in cancer cells, we examined whether exogenous Ets-1 expression affects the survival of HeLa cells treated with PJ-34." (PMID 23405229, 2013). "Considering the findings presented in this study, it is possible that Nrf2-mediated induction of Ets-1 is central to the regulation of antioxidant capacity in cancer cells, and thus this may be a promising focus for future studies." (PMID 24280356, 2013). "Ets-1 expression is tightly regulated in adult tissues and its overexpression is often related to invasive diseases, such as rheumatoid arthritis, glomerulonephritis and many cancers." (PMID 23405229, 2013). "Our finding that NO activation of Ras, via SNO results in Ets-1 activation suggests that other Ras-mediated pathways may also activated by NO in human cancer." (PMID 22971289, 2012). "In many cancers, the proto-oncogene ETS1 plays a role in chemoresistance and invasion." (PMID 22894607, 2012). "However, results of our siRNA experiments in three different cancer cell lines show positive regulation of CIP2A expression by ETS1." (PMID 21445343, 2011).